TNF (tumor necrosis factor)
Diseases named in the same sentence as TNF in open-access papers (continued):
Sharing a sentence is not in itself a finding about the gene and the disease.
schizophrenia (continued). "A meta-analysis demonstrated high protein levels of pro-inflammatory cytokines (e.g., IL-6 and TNFα) in the peripheral blood in schizophrenia patients, where patterns of the increased cytokines are different between phases of illness." (PMID 38673876, 2024). "Research has revealed variations in particular inflammatory cytokines in those with schizophrenia, including changes in levels of interleukins (IL) and tumor necrosis factor (TNF)." (PMID 38979494, 2024). "It is recommended that miRNA levels assess by disease severity and clinical profiles to provide reliable evidence for the concoctions between higher levels of IL-6, IL-1β, TNF-α, and mi-RNAs in patients with schizophrenia in comparison with controls." (PMID 37644489, 2023). "Compared with healthy people, IL-6 and TNF-α levels were significantly increased in schizophrenia patients, while IL-2, IL-4 and IFN-γ levels were significantly decreased." (PMID 37582716, 2023). "Another study found a marginal association for family history of schizophrenia after interaction analysis between 5-HTTLPR and tumor necrosis factor (TNF) rs61525 polymorphisms." (PMID 37109044, 2023). "For instance, interleukin-6 (IL-6), tumor necrosis factor-α (TNF-α), and oxidative stress have been found in high levels in both keratoconus and schizophrenia patients." (PMID 37602110, 2023). "In a study which evaluated the proinflammatory state in the first episode of schizophrenia, IL-6 was recognized as a state marker for acute exacerbations and tumor necrosis factor alpha (TNFα) as a trait marker of schizophrenia." (PMID 37032951, 2023). "For example, serum levels of interleukin-6 (IL-6) and tumor necrosis factor-α (TNF-α) are found to be raised in acute psychotic relapses in patients with schizophrenia." (PMID 37376644, 2023). "The researchers found a significant interaction between sex and subject group, such that females with schizophrenia were more likely to have decreased levels of maternal TNF-α as compared to males with schizophrenia and females in the control group." (PMID 37123361, 2023). "The gene expression of DNA sequences coding for proteins involved in TNF-α and IL-17 signaling processes appears more pronounced in schizophrenia patients than in healthy ones." (PMID 37371435, 2023). "Atypical neuroleptics, such as risperidone, reduced serum IL-6 in schizophrenia patients, along with reducing IL-10 and TNF-α in first episode patients, which also coincided with the results of our study." (PMID 37189796, 2023). "In contrast, whole blood stimulation studies in schizophrenia showed elevated concentrations of IL-6, TNF-α, and IL-1β post-TLR2 stimulation, and increased IL-1β alone post-TLR4 and 8 stimulation." (PMID 37627253, 2023). "The majority of studies have shown increased levels of TNF-α in the first episode of schizophrenia and during its exacerbations." (PMID 37189796, 2023). "A previous study suggested that proinflammatory cytokine (IL-1β, IL-6, IL-8, and TNFα) release was enhanced in whole blood from schizophrenia patients." (PMID 37210391, 2023). "Immune cells mainly produced TNF-α, which has a remarkable role in the pathogenesis of schizophrenia by affecting the dendritic development of cortical neurons." (PMID 37644489, 2023). "An increased risk of schizophrenia has also been implied because of the association between variations of tumor necrosis factor-α and interleukin-10 genes and susceptibility in both CMV infections and schizophrenia." (PMID 37376644, 2023). "Elevated circulating (soluble) TNF protein is consistently found in chronically-ill people with schizophrenia across multiple cohorts." (PMID 35027554, 2022). "We found higher TGF-α (p = 0.014), IFN-γ (p = 0.036), IL-5 (p < 0.001), IL-6 (p = 0.047), IL-8 (p = 0.005), IL-10 (p <0.001), IL-15 (p = 0.007), IL-1RA (p = 0.007), and TNF-α (p < 0.001) levels in patients with schizophrenia than in healthy individuals." (PMID 36556337, 2022).
schizophrenia (continued). "The first major finding of this study is that IL-23, IL-6, IL-17, and TNF-α were considerably greater in MNP than in SNP, while IL-1β, IL-22, G-CSF, IL-21, IL-17, IL-10, and TNF-α were significantly higher in schizophrenia than in controls." (PMID 36256663, 2022). "We found higher TGF-α (p = 0.014), IFN-γ (p = 0.036), IL-5 (p < 0.001), IL-6 (p = 0.047), IL-8 (p = 0.005), IL-10 (p < 0.001), IL-15 (p = 0.007), IL-1RA (p = 0.007), and TNF-α (p < 0.001) levels in patients with schizophrenia compared with healthy individuals." (PMID 36556337, 2022). "A recent study has shown that schizophrenia patient-derived microglia have an enhanced response to LPS, with an increased secretion of TNF-α." (PMID 35844244, 2022). "In the present study, we recruited a relatively larger sample of patients with schizophrenia and measured more plasma inflammatory cytokines, including IL-1β, IL-2, IL-4, IL-6, IL-8, IL-10, IL-12, IL-17, TNF-α, IFN-γ, and CRP." (PMID 36341400, 2022). "Increments in cytokines such as IL-1β, TNF-α, IL-6, and IL-10 have frequently been described in schizophrenia." (PMID 36256663, 2022). "A considerable number of studies, including meta-analyses, have revealed elevated levels of IL-6 and TNF-α in various groups of patients with schizophrenia." (PMID 36556337, 2022). "Research has found that NE acts upon βARs on human cord dendritic cells to inhibit the LPS stimulated production of IL-23, TNF-α and IL-6, which are cytokines that have been found to be increased in schizophrenia patients." (PMID 35844244, 2022). "As well as the presence and relationship of cytokines (IL-33, TGF-β, and TNF-α) in the mentioned groups, taking into account that all respondents were in a stable phase of schizophrenia." (PMID 35958655, 2022). "We recently created a novel neuroimmunotoxic pathway index in schizophrenia, particularly deficit schizophrenia, by connecting IL-6, IL-23, and IL-17 to critical actors such as IL-21, IL-22, and TNF-α." (PMID 36429996, 2022). "Males with schizophrenia had statistically significantly higher levels of IL-10 (p = 0.017), IL-5 (p = 0.048), and TNF-α (p = 0.025) than did healthy age-matched males." (PMID 36556337, 2022). "One type of regulatory macrophage (M2), M2b, can secrete some cytokines known to be elevated in schizophrenia including IL-1, IL-6, and TNF-a." (PMID 35844224, 2022). "Tumor necrosis factor alpha (TNFα) also decreased in schizophrenia (g: −0.34; CI −0.68 to −0.01; p = 0.047) and in MDD (g: −1.02; CI −1.79 to −0.25; p = 0.009)." (PMID 33653423, 2021). "Increase in the plasma levels of proinflammatory cytokines, such as IL-1β, IL-6, and TNF-α, have been consistently reported in patients with schizophrenia." (PMID 34393855, 2021). "Of note, the situation with high IL-6 and low TNF-α observed in ADHD youth in our study has also been observed in patients with Schizophrenia during both exacerbation and remission." (PMID 34413283, 2021). "Changes in TNF signaling in the brains of patients with psychiatric disorders (schizophrenia, bipolar disorder) have been an area of therapeutic interest." (PMID 34767585, 2021). "The mean TNF-α level in FEDN patients with schizophrenia was 24.95 (7.48, 43.12) pg/mL after treatment." (PMID 34763685, 2021). "SERPINA3 mRNA was increased by 414% (F = 21.49, df = 1,52, p < 0.0001) in schizophrenia cases relative to controls and TNFα mRNA was increased by 132% (F = 3.90, df = 1,53, p = 0.050) in cases compared with controls." (PMID 31168068, 2021). "Meta-analyses for MDD, schizophrenia, and BD all found elevated blood levels of interleukin (IL)-1β, soluble interleukin-2 receptor (sIL-2R), and tumor necrosis factor (TNF)-α8,12,13." (PMID 34078872, 2021). "BDNF and TNFα are possibly shared markers of an active first-episode of schizophrenia and MDD, since these blood compounds tend to normalize following treatment." (PMID 33653423, 2021).
schizophrenia (continued). "There are no consistent results on the relationship between TNF-α and psychiatric symptoms in patients with schizophrenia or on the relationship between changes in the TNF-α levels and psychiatric symptoms." (PMID 34763685, 2021). "The data shown in depicted that cytokines including IL-2, IL-6, and TNF-α play a considerable role in the development of schizophrenia." (PMID 33995058, 2021). "A recent analysis of the inflammatory response to an induced microglia-like phenotype (iMG) has shown that cells from patients with schizophrenia have a stronger response to lipopolysaccharide, with TNF-α protein secretion most prominently observed." (PMID 34763685, 2021). "Male schizophrenia patients tended to have a smaller change in TNFα after treatment compared with female schizophrenia patients (g: 0.08; CI 0.03–0.12; p < 0.001)." (PMID 33653423, 2021). "Taken together, both immune factors IL-6 and TNFα are increased in schizophrenia and MDD at disease onset." (PMID 33653423, 2021). "The abnormal expression of TNF-α pathway in schizophrenia patients has been well documented in the existing literature." (PMID 34526062, 2021). "One possible reason for this discrepancy is that antipsychotic therapy reduces the production of certain proinflammatory cytokines in schizophrenia, including TNFα." (PMID 38601098, 2021). "The latest report showed that patients with schizophrenia who are treated with clozapine or olanzapine alone and have metabolic problems have significantly higher plasma IL-6 and TNF-α levels than healthy controls." (PMID 33774704, 2021). "Brain autopsies of patients with schizophrenia showed 2.3-fold increased concentrations of TNF-α protein and mRNA compared to the normal population." (PMID 34763685, 2021). "In the case of IL-1β, IL-6 and TNF-α, their potential roles as trait markers of schizophrenia seem to be supported by correlations with the results of neuroimaging studies,; and in the case of TNF-α and IL-6, also with the experience of early childhood trauma." (PMID 34501305, 2021). "Among these, the study of Smith and Maes proposed that in schizophrenia, chronically activated macrophages and T lymphocytes produce cytokines, such as TNF-α, IL-1, IL-2, IFN-α, and IFN-γ, that have a key role in this disorder's development." (PMID 33746786, 2021). "In this meta-analysis, we found evidence that growth factor BDNF increase and immune factor TNFα decrease following treatment in drug-naïve first-episode patients with either schizophrenia or MDD." (PMID 33653423, 2021). "A significant positive correlation was found between the serum TNF-α levels and the serum Kyn levels (r = 0.53, p = 0.0026) and the Kyn/Trp value (r = 0.67, p = 0.000046) in the schizophrenia group." (PMID 34393855, 2021). "Data from 62 studies, analyzed IFN-γ, IL-4, IL-2, soluble IL-2 receptor (sIL-2R), IL-1β, IL-1 receptor antagonist (IL-1RA), TNF-α, IL-6, soluble IL-6 receptor (sIL-6R), and IL-10 in schizophrenia." (PMID 33746786, 2021). "Schizophrenia patients have been shown to have high levels of inflammatory cytokines, such as TNF-α, IL-1β, and IL-6, as well as high microglial activation throughout the brain as shown by PET scans and postmortem biopsies." (PMID 33854417, 2021). "Inflammatory cytokines, especially TNF-α and IL-6, are the primary molecular targets for schizophrenia." (PMID 34393855, 2021). "Our results support the presence of sex differences in the association between TNF-α, MDA, and their interaction with psychopathological symptoms of patients with schizophrenia." (PMID 34526062, 2021). "Previously, we have reviewed the many neurotoxic effects of increased TNF-α levels in schizophrenia, and especially in deficit schizophrenia." (PMID 34831151, 2021). "We have not looked forward and examined the signaling pathways activated by biomarker candidates of schizophrenia, such as tumor necrosis factor-alpha, IL-1β, and IL-6." (PMID 33402704, 2021).
schizophrenia (continued). "Proinflammatory cytokines, including interleukin-1β (IL-1β), IL-6, and tumor necrosis factor-α (TNF-α), are thought to contribute to the pathogenesis of psychiatric symptoms in schizophrenia by Kyn pathway activation." (PMID 34393855, 2021). "TNF-α is one of the most important pro-inflammatory cytokines and contributes heavily to the pathophysiological process of schizophrenia." (PMID 34526062, 2021). "Higher levels of circulating cytokines, mostly IL-6 and tumor necrosis factor alpha (TNFα), were found in patients with schizophrenia and bipolar disorder." (PMID 34298890, 2021). "An increased level of inflammatory cytokines, especially IL-6 and TNF-α, has also been found in the circulation of acutely ill patients with schizophrenia, bipolar disorder, and MDD." (PMID 34650454, 2021). "There was a significant positive correlation between serum IDO levels and serum TNF-α levels in all schizophrenia patients at baseline (r = 0.057, P = 0.021)." (PMID 34802039, 2021). "Similar associations have been reported in patients with established schizophrenia for TNF-α and IL-6, in patients with first episode psychosis for IFN-γ and more recently in individuals at ultra-high risk of psychosis with TNF-α and IL-6." (PMID 33667853, 2021). "Elevated maternal levels of inflammatory cytokines, such as interleukin (IL)-8 and tumor necrosis factor (TNF)-alpha, increase the risk of schizophrenia in the offspring." (PMID 34199231, 2021). "Significantly higher plasma levels of IL-6, IL-10, and TNF-α were, however, detected in schizophrenia patients treated with olanzapine or clozapine, as compared with normal controls." (PMID 33746786, 2021). "The Kruskal-Wallis H test revealed significant differences in the TNF-α levels between patients with schizophrenia and healthy controls (p < 0.001)." (PMID 34763685, 2021). "Younger patients with schizophrenia showed more change in TNFα levels following treatment compared with older patients with schizophrenia (g: 0.14; CI 0.02–0.26; p = 0.019)." (PMID 33653423, 2021). "MDD patients also showed decreased TNFα after treatment with a large effect size (g: −1.02; CI −1.79 to −0.25; p = 0.009; I2 = 91%) compared with schizophrenia patients." (PMID 33653423, 2021). "Increasing evidence indicates that dysregulated TNF-α and oxidative stress (OxS) contribute to the pathophysiology of schizophrenia." (PMID 34526062, 2021). "Childhood trauma also seems to play a mediating role between elevated TNF-α levels and the changes in gray matter visible in MRI studies in patients with schizophrenia." (PMID 34501305, 2021). "Network analyses indicate tumor necrosis factor (TNF), interleukin-4 (IL-4), and interferon-γ (IFNγ) as predominant functional nodes in the relationship between lithium response and schizophrenia genetic predisposition." (PMID 33804842, 2021). "We found diagnostic increases in SERPINA3, TNFα, IL1β, IL6, and IL6ST transcripts in schizophrenia compared with controls (p < 0.02–0.001)." (PMID 31168068, 2021). "Psychopharmacological treatment has modulating effects on BDNF and TNFα in drug-naïve first-episode patients with either schizophrenia or MDD." (PMID 33653423, 2021). "Correspondingly, our previous studies have also found that TNF-α, the OxS system, and their interaction were involved in the pathophysiology of schizophrenia." (PMID 34526062, 2021). "Depression and schizophrenia patients exhibit dysregulation in their immune function, and IL-1β, IL-2r, IL-6, and TNF-α have been identified as biomarkers of schizophrenia." (PMID 33613171, 2020). "We determined the plasma levels of six cytokines (IL-1β, IL-4, IL-6, IL-10, IL-12 and TNF-α) in schizophrenia patients and healthy controls." (PMID 32038109, 2020). "The results of the present systematic review revealed the following cytokines as possible candidates for deregulatory mechanisms on the kynurenine pathway in schizophrenia: TNF-α, IFN-γ, IL-6, IL-4, IL-8, and IFN-α." (PMID 32061259, 2020).
schizophrenia (continued). "Many studies by our team and others have suggested that the pathogenesis of schizophrenia involves an alteration of peripheral immune system that leads to altered blood levels of TNF-alpha." (PMID 31954374, 2020). "In the present study, we found that schizophrenia patients with olanzapine or clozapine monotherapy exhibited increased plasma levels of IL-6, IL-10, and TNF-α, which was also observed in many previous studies." (PMID 33324265, 2020). "In conclusion, the present systematic review found a relationship of elevated IL-6, IL-8, and TNF-α concentrations with the kynurenine pathway in schizophrenia." (PMID 32061259, 2020). "This indicated that the patients with the TT genotype had reduced TNF-alpha levels and an earlier onset age of schizophrenia and suicide initiation." (PMID 31954374, 2020). "A recent study compared TSPO PET of schizophrenia patients and controls with combined peripheral and CSF measures of IL1β, IFNγ, IL-10, IL-6 and TNF-α." (PMID 32179746, 2020). "Available evidence suggests that patients with schizophrenia have higher levels of inflammatory cytokines such as IL-1, IL-6, and tumor necrosis factor-α." (PMID 33372679, 2020). "Meta-analysis data indicate that several cytokines including TNF-α levels are elevated in serum of schizophrenia patients." (PMID 32341334, 2020). "At 37 days, we observed no gross differences of size, shape, or macroscopic deformities in the TNF exposed control (C+TNF) or schizophrenia (SZ+TNF) organoids compared to the C or SZ organoids that did not receive the cytokine." (PMID 33005129, 2020). "These cytokines were selected to include those (IL-6, IL-1β, TNFα) that can be increased in the serum of patients with schizophrenia or autism spectrum disorders." (PMID 33288794, 2020). "The exacerbated decrease in ABCG2 in the “high inflammation” schizophrenia subgroup is consistent with evidence showing that treatment with IL-1β, IL-6 and TNFα reduces both mRNA and protein expression of endothelial ABCG2 in vitro." (PMID 30214039, 2020). "Activated inflammatory microglia release pro-inflammatory cytokines such as TNF-α, IL-1β, and IL-6 and the specific influence of these inflammatory cytokines on neurotransmitter systems reportedly leads to schizophrenia and other psychiatric disorders." (PMID 32341334, 2020). "Treatment with typical neuroleptics, haloperidol, and perazine, normalized the release of IL-1β and TNF-α by inhibiting monocyte activity in schizophrenia patients." (PMID 32341334, 2020). "It is also worth noting that many of the cytokines altered in the maternal serum are also elevated in the blood of patients with schizophrenia, including IL-1β, IL-2, IL-6, IL-12 and TNF-α." (PMID 30691477, 2019). "Inflammation is present in bipolar disorder and schizophrenia indexed by inflammatory cytokines IL-6, IL-1Ra, IL-1β TNF- α, and also by NO production via iNOS, superoxide dismutase catalase, and glutathione peroxidase." (PMID 30918489, 2019). "A recent meta-analysis of 18 schizophrenia, 16 bipolar disorder, and 12 major depressive disorder studies revealed significant elevations of IL-6, TNF-α, IL-1 receptor antagonist, and soluble IL-2 receptor in acute episodes of all groups compared to controls." (PMID 29803226, 2018). "Recently, one study found that TNF-α and IL-1β were increased in the blood of first onset and acute relapse patients with schizophrenia." (PMID 29867314, 2018). "In our previous study, we found that polymorphic sites of gene receptor 1 of tumor necrosis factor (TNFR1) also were connected with excitement symptoms in paranoid schizophrenia." (PMID 30254506, 2018). "Previous reports of genome-wide association studies have proved a significant association between schizophrenia and markers close to the major histocompatibility complex (MHC) region which contains gene coding for LTA and TNFα." (PMID 30627222, 2018).